MIR548A2 (microRNA 548a-2)
Synonyms: hsa-mir-548a-2; MIRN548A2
Gene: MicroRNA gene on chromosome 6 (135,239,160 to 135,239,256, forward strand). Ensembl gene ENSG00000207689.
Diseases named in the same sentence as MIR548A2 in open-access papers:
MIR548A2 is named in the same sentence as 1 disease in open-access papers, as found by Europe PMC text mining. Sharing a sentence is not in itself a finding about the gene and the disease.
MIR548A2 shares sentences with these, for which no sentence is quoted: melanoma (1 paper).